INS (insulin)
Diseases named in the same sentence as INS in open-access papers (continued):
Sharing a sentence is not in itself a finding about the gene and the disease.
Hyperglycemia (continued). "Decreased insulin sensitivity in the liver can result in increase in glucose production leading to hyperglycemia." (PMID 31215434, 2019). "Insulin is a peptide hormone secreted in response to postprandial hyperglycemia from pancreatic beta−cells in blood circulation." (PMID 31474827, 2019). "The most common reasons for DKA in PT1D are insulin omission and, among insulin pump users, failure to take extra insulin with a pen or syringe when hyperglycemia occurs." (PMID 31295949, 2019). "PPAR-γ activation reduces hyperglycemia by increasing sensitivity to peripheral insulin and decreasing the production of hepatic glucose." (PMID 31562809, 2019). "Our results provide mechanistic insight into the beneficial effects of exercise on hyperglycemia and insulin action in skeletal muscle of diabetic GK rats." (PMID 31338039, 2019). "Functionally, overexpression of FGF21 attenuated hyperglycaemia and insulin storage, improved glucose tolerance and preserved islet β‐cells from apoptosis." (PMID 30461198, 2019). "Eleven hours later, the insulin infusion was resumed to treat DKA after laboratory findings revealed hyperglycemia, an elevated β-hydroxybutyrate, and anion gap metabolic acidosis." (PMID 31523559, 2019). "Further, resveratrol has been shown to reduce hyperglycemia and ameliorate dysregulated insulin signaling." (PMID 30800211, 2019). "Cleavage of His-Ala from the N-terminus of GLP-1 by DPP4 inactivates GLP-1 and its effect on insulin release stimulation and its inhibition of the release of glucagon, resulting in hyperglycemia." (PMID 30972338, 2019). "Ultimately, the metabolism of glucagon hinges upon the concentration of glucose, either by direct secretion during hypoglycaemia, or indirectly via insulin-mediated inhibition during hyperglycemia." (PMID 31829209, 2019). "These patients require continuous exogenous insulin therapy, with insufficient doses leading to extreme hyperglycemia or diabetic ketoacidosis." (PMID 30781427, 2019). "These metabolic aberrations were more strongly predictive of deterioration of insulin sensitivity and impaired post-load glucose levels over long-term follow-up than worsening of fasting hyperglycaemia." (PMID 31584131, 2019). "If hyperglycemia is at least partially consequent to a shift in glucose metabolism and insulin resistance, then what does that imply for the treatment of hyperglycemia in critically ill patients?" (PMID 30972338, 2019). "In this study, the pancreas injury of mice was induced by STZ, and the dysfunction of insulin secretion and hyperglycaemia were observed due to damaged β cells of pancreas." (PMID 30800168, 2019). "The stimulation of glucose uptake into muscle is the most important means whereby insulin reduces postprandial hyperglycemia, and GLUT4 plays a pivotal role in maintaining the blood glucose level." (PMID 31100973, 2019). "Our studies suggest that hyperglycaemia impairs mitochondrial metabolism and reduces the glucose-induced increase in ATP that is required for insulin secretion." (PMID 31171772, 2019). "Metreleptin replacement therapy was shown to increase insulin sensitivity and insulin secretion, and to decrease hyperglycemia, hypertriglyceridemia, liver steatosis, and reproductive abnormalities associated with LD." (PMID 31300002, 2019). "Independent of the virus, E4orf1 protein promotes glucose uptake in adipocytes, myoblasts and reduces glucose output from hepatocytes, and in vivo, it improves high fat induced hyperglycemia, and reduces the response of endogenous insulin to glucose load." (PMID 31127081, 2019). "Since mitochondrial oxidative capacity, antioxidant status, and inflammation are intrinsically connected, RT-mediated improvements of those systems synergistically ameliorate HbA1c, insulin, and hyperglycemia in patients with T2D." (PMID 30621076, 2019).
Hyperglycemia (continued). "Nevertheless, despite such advances in insulin development, many patients with type 1 diabetes (T1D) or insulin-dependent type 2 diabetes (T2D) remain unable to control postprandial hyperglycemia and hence meet or maintain HbA1c targets." (PMID 30746556, 2019). "Oral administration of S-allyl cysteine sulphoxide isolated from garlic to alloxan diabetic rats for one month ameliorated hyperglycaemia in treated rats, which was comparable to glibenclamide and insulin treated rats." (PMID 31118963, 2019). "This annual saving of £147.75 per patient in favor of degludec included a 22% (£47.61) reduction in basal insulin cost and a 59% (£100.14) reduction in the cost of hyperglycemia with ketosis events." (PMID 31543973, 2019). "As a result, hyperglycemia and hyperinsulinemia occur because of the reduced glucose uptake from tissues in response to insulin and the consequent increase in insulin secretion by pancreatic beta cells, in the attempt to control glucose homeostasis." (PMID 31246177, 2019). "To control hyperglycaemia, initially we titrated daily insulin dosage, and then intravenous insulin treatment was practiced with the consequent normalization of liver enzymes." (PMID 30616577, 2019). "Treatment of iFIRKO mice with antioxidants postponed and reduced hyperglycaemia by increasing insulin sensitivity." (PMID 31309261, 2019). "Insulin resistant promotes hyperglycemia thus leading the pancreas to produce more insulin to maintain glucose homeostasis." (PMID 31906216, 2019). "DM covers etiologically different metabolic disorders that exhibit the same phenotype, hyperglycemia, due to either insufficient insulin production relative to insulin demand or insulin resistance." (PMID 31818369, 2019). "Our findings confirm that the personalised insulin calculator is safe and effective for the correction of hyperglycaemia prior to FDG administration." (PMID 30737563, 2019). "Defects in the glucose-sensing machinery have been shown to impair insulin secretion and subsequently the development of severe hyperglycemia." (PMID 31781030, 2019). "Reducing the insulin requirements and increasing carbohydrate intake before exercise are suitable approaches to prevent exercise-induced hyperglycemia." (PMID 30781593, 2019). "A carbohydrate-restricted diet is a logical intervention for those suffering from hyperglycemia and hyperinsulinemia and has consistently shown remarkable reductions in fasting and postprandial glucose and insulin levels." (PMID 31700709, 2019). "The enzyme activity and protein expression of ACE2 were both attenuated by administration of insulin, rosiglitazone and metformin, agents known to correct hyperglycaemia." (PMID 30591810, 2019). "Here, we treated HSD fed rats with high dose statins using atorvastatin (20 mg/kg) and simvastatin (30 mg/kg) for a shorter duration (30 days) to push hard on the prospect of statins worsening hyperglycemia and insulin signaling." (PMID 31217552, 2019). "DPP-IV inhibitors shorten the inactivation of glucagon-like peptide 1 (GLP-1), permitting the incretin to stimulate insulin release, thereby combating hyperglycemia." (PMID 31165274, 2019). "Autoimmune destruction of the insulin-producing beta cells in the pancreas results in hyperglycemia and lifelong insulin dependency." (PMID 31616039, 2019). "Recent evidence demonstrates the beneficial role of Sirtuin 1 (SIRT1), an NAD+ dependant deacetylase, in improved insulin sensitivity and glucose homeostasis, linking hyperglycaemia and SIRT1 downregulation." (PMID 30696833, 2019). "A cascade of anatomical and physiological alterations and subsequent metabolic adaptations exert beneficial effects on insulin production and sensitivity after bariatric surgery, leading to amelioration of hyperglycemia or even restoration of euglycemia." (PMID 31480306, 2019). "Bolus insulin therapy aims to mimic the normal mealtime insulin response to reduce postprandial hyperglycemia while avoiding hypoglycemia." (PMID 30746556, 2019).
Hyperglycemia (continued). "VDAC1 inhibitors, including metformin, restore insulin secretion in T2D islet donors and prevent hyperglycemia in diabetic mice." (PMID 30293774, 2019). "When severe hyperglycaemia presents (at 9–12 weeks of age), pancreatic insulin content is reduced by 97%." (PMID 30635569, 2019). "The glycemic index and load of foods are important in the management of hyperglycemia and minimizing need for exogenous insulin in type I diabetes and the presence of hyperinsulinemia in type II." (PMID 31950066, 2019). "It was widely used in studies investigating of DM, as it specifically targets β-cells and reduces blood insulin levels, leading to hyperglycemia and mimicking DM pathology." (PMID 30805250, 2019). "A dysfunctional regulation of FFA that leads to an increase demand for insulin, a demand that is stimulated by both glucose and FFA, which in turn, puts the individuals at higher risk of hyperglycemia when beta-cell compensation fails." (PMID 31499737, 2019). "This reflects the antioxidant potential theaflavin and metformin in long-term control of hyperglycemia through insulin secretion." (PMID 32219004, 2019). "This conflict has been resolved in that hyperglycemia only occurs when insulin secretion is insufficient to overcome barriers to insulin action [1•]." (PMID 31776781, 2019). "Though there are many factors that contribute to the progression of diabetes, it is important to recognize that ultimately a failure of β-cells to secrete sufficient amounts of insulin is what results in hyperglycemia and the diagnosis of T2DM." (PMID 31258514, 2019). "The intraperitoneal glucose administration can exclude the implication of a response driven by incretin hormones, which are gut peptides that are secreted after nutrient intake and stimulate insulin secretion together with hyperglycemia." (PMID 31861348, 2019). "This circumstance probably related to the higher insulin treatment rate in the stress hyperglycaemia group." (PMID 31052350, 2019). "Because hyperglycemia can impair the myocardial tolerance to ischemia-reperfusion and knowing that insulin is cardioprotective, we included these parameters in the bundle of care of the ProCCard study, in conjunction with RIPC and sevoflurane." (PMID 31511041, 2019). "In particular, insulin administration for hyperkalemia and uncomplicated hyperglycemia were frequent culprits." (PMID 31539342, 2019). "Flavonoids have the ability to stimulate the β-cells to release insulin, ameliorate insulin secretion, decrease hyperglycemia, and restore the body weight." (PMID 31579450, 2019). "We therefore conclude that the therapy with both insulin and glucagon performs better than the therapy with only insulin, as the risks for both hypoglycemia and hyperglycemia are reduced and glucose fluctuations are suppressed." (PMID 30893335, 2019). "Significantly decreased levels of insulin and elevated blood glucose (hyperglycemia) are observed in the plasma of diabetic rats." (PMID 31231496, 2019). "Treatment of db/db mice with VDAC1 inhibitor prevents hyperglycemia, and maintains normal glucose tolerance and physiological regulation of insulin secretion." (PMID 30293774, 2019). "Disease progression is potentiated by a reduced capacity of β-cells to undergo metabolic compensation, leading to additional β-cell stress and dysfunction due to hyperglycemia, a process culminating in a requirement for insulin replacement therapies." (PMID 30679186, 2019). "The most common hyperglycaemia treatment at recruitment was basal-bolus insulin in 21 (49%) or basal insulin alone in ten (23%) participants." (PMID 30935872, 2019). "It has also been reported that catechin and epicatechin reduce hyperglycemia and hepatic glucose output, while quercetin improves insulin-dependent glucose uptake." (PMID 31861633, 2019). "Accordingly, HFD/STZ-induced rats in this study exhibited hyperglycemia, and impaired glucose tolerance and insulin secretion." (PMID 31887984, 2019).
Hyperglycemia (continued). "The rise of circulating free fatty acids in turn increases hepatic gluconeogenesis and glycogenolysis, as well as increasing insulin secretion by the pancreas, resulting in hyperglycaemia." (PMID 31379754, 2019). "When insulin shortage occurs, the activity of this process is disturbed, and the rate of glucose uptake decreases, resulting in hyperglycaemia in the extracellular space." (PMID 31089886, 2019). "IR causes reduced sensitivity to insulin action in the cells of fat, liver, and skeletal muscle so that normal levels of insulin fail to efficiently reduce blood glucose, leading to hyperglycemia." (PMID 30744700, 2019). "Hyperglycemia and insulin both influence MALAT1 expression in HepG2 cells, whereas only insulin affects MALAT expression in LX-2 cells." (PMID 30931332, 2019). "The 24-month-old rats needed more insulin to maintain postprandial normoglycemia; nevertheless, hyperglycemia occurred at 240 min after fat administration." (PMID 31405194, 2019). "The present results are also consistent with those of a previous study that showed that green tea catechin ameliorated hyperglycemia by improving adipose insulin sensitivity in KK-Ay mice." (PMID 31100973, 2019). "Aqp7 knockout mice displayed hyperinsulinemia with either hyperglycemia or normoglycemia, or normal insulin and glucose levels." (PMID 31614661, 2019). "This outcome describes the causal inverse relationship between the neurally mediated pre-absorptive insulin and the postprandial hyperglycemia and hyperinsulinemia reported by previous studies." (PMID 30685858, 2019). "In the T2DM model, hyperglycemia is attributable to the sum of insulin insensitivity and impaired insulin secretion." (PMID 31805752, 2019). "Hyperglycemia can be induced by two different mechanisms; one is reduction of insulin secretion from pancreatic β-cells, and the other is increased insulin resistance in the target organs." (PMID 31661025, 2019). "Although the therapy corrects anaemia and hyperglycaemia, there are reports of patients requiring insulin therapy and regular blood transfusions in adulthood." (PMID 31137773, 2019). "Modest insulin perturbations and hyperglycemia, on-target effects of p110α blockade, were also observed indicating target engagement." (PMID 30073466, 2019). "Experimental animal models of type 1 diabetes have also shown that significantly upregulated levels of circulating unmethylated INS DNA are detectable before the onset of hyperglycemia." (PMID 31428654, 2019). "The more pronounced the hyperglycaemia and the ketosis are, the greater is the amount of insulin required for normalization." (PMID 31089886, 2019). "Chronic hyperglycemia triggers severe diabetic complications such as dysfunction of insulin-stimulated glycogen synthesis and increased glucose output." (PMID 31089370, 2019). "PPAR-γ expression was studied in the obese mice and IR cells by qRT-PCR, because activated PPAR-γ has been reported to reduce hyperglycemia by increasing peripheral insulin sensitivity and alleviating the production of hepatic glucose." (PMID 31562809, 2019). "GLP-1 introduction naturally prevents hyperglycemia, while in the vessels of group 5 mice lung tissue, a significant increase in the expression of insulin was found (the 188th day)." (PMID 30836679, 2019). "With decreased insulin sensitivity or insulin resistance, the body is unable to effectively combat hyperglycemia, allowing for consistent states of high blood glucose." (PMID 31616284, 2019). "Our research provides a new scope for molecular mechanisms on the improvement of hyperglycemia and insulin sensitivity by exercise." (PMID 31338039, 2019). "By 7–12 weeks, hyperglycemia is apparent; at this point, pancreatic β-cell compensation occurs, and increased insulin levels bring glucose homeostasis under control, after which they fall as the mouse ages." (PMID 30823474, 2019).
Hyperglycemia (continued). "Insulin is one of the oldest valuable antidiabetic medications available and also the most effective agent in dropping hyperglycemia when used in appropriate doses." (PMID 31915711, 2019). "In STZ-induced mice, genistein improved glucose tolerance, hyperglycemia, and the level of circulating insulin." (PMID 31480505, 2019). "After 12 weeks of HF feeding and prior to intervention with L. brevis, diet-induced hyperglycaemia and insulin insensitivity was confirmed in a subset of mice from the HFC, compared with a subset of mice from the LFC." (PMID 31704943, 2019). "The destruction of β islets results in an absolute or relative deficit of insulin and hyperglycemia." (PMID 31652638, 2019). "Persistent hyperglycemia reduces β-cell function and insulin action by attenuation of insulin-mediated glucose transport and impairment of glucose-induced insulin secretion, which subsequently leads to deterioration of β-cell function." (PMID 31860682, 2019). "Akt2 knockout impaired glucose uptake in isolated soleus and extensor digitorum longus muscles on exposure to a low concentration of insulin, and Akt2 knockout mice indeed exhibited hyperglycemia and glucose intolerance." (PMID 30735546, 2019). "T1D results from the autoimmune destruction of the pancreatic insulin-producing β-cells, which leads to hyperglycaemia and the lifelong dependence on exogenous insulin therapy." (PMID 30956666, 2019). "Insulin contributes to regulating hyperglycemia and inhibiting greater HFC by decreasing hepatic de novo lipogenesis." (PMID 31554294, 2019). "Diabetic mice presented insulitis, hyperglycaemia, hypoinsulinemia and hyperglucagonemia along with lower pancreatic insulin content." (PMID 31266981, 2019). "Theoretically, it is better to oat and oat peptides in physiological function and physicochemical properties, so the effects of OOPs on hyperglycemia, insulin metabolism, oxidative stress and hepatic enzymes were evaluated for the first time." (PMID 30717466, 2019). "For instance, during stress and infections, the patient usually struggles with hyperglycemia and injects frequent insulin to lower his or her BG levels." (PMID 31042157, 2019). "Ingestion of a high-fat and/or carbohydrate meal, which results in temporary hyperglycemia and hyperlipidemia, prompts oxidative stress, which seems to be more extended in subjects who are obese or insulin-resistant." (PMID 31817857, 2019). "Hyperglycemia results if IR occurs when insulin cannot increase glucose uptake or suppress glucose production in the liver." (PMID 31540136, 2019). "The increase in mitochondrial ROS induces and/or worsens ER stress, an event that is prone to occur in β-cells due to the high demand for the synthesis and secretion of insulin in response to hyperglycemia." (PMID 31487953, 2019). "The hallmark of type 1 diabetes (T1D) is immune-mediated destruction of insulin secreting β-cells of the pancreatic islets of Langerhans, resulting in hyperglycemia and lifelong dependency on exogenous insulin." (PMID 30733517, 2019). "The SDT rat spontaneously develops hyperglycaemia as a result of reduced insulin secretion due to the dysfunction of pancreatic islet tissues." (PMID 30836664, 2019). "There he also received ceftriaxone; hydrocortisone; insulin infusion for hyperglycemia; cardioversion for ventricular tachycardia; and, later, intubation, ventilation, and continuous venovenous hemofiltration." (PMID 30624597, 2019). "P.g and T.d supernatants demonstrated an increase in insulin secretion to fivefold at hypo- and hyperglycemia, yet stimulation from hypo- to hyperglycemia stays in the same ratio." (PMID 30039349, 2019). "Glucagon-like peptide 1 (GLP-1) receptor agonists and dipeptidyl dipeptidase 4 (DDP-4) inhibitors increase insulin secretion and decrease hyperglucagonemia, thereby lowering hyperglycemia." (PMID 31776781, 2019).